OR51L1 (olfactory receptor family 51 subfamily L member 1)
Description:
Odorant receptor.
Synonyms: OR11-31
Tractability: Antibody: its Gene Ontology location is reachable by antibodies, with high confidence; UniProt places it where antibodies can reach, with medium confidence; UniProt predicts a signal peptide or a membrane-spanning region.
Gene: Protein-coding gene on chromosome 11 (4,994,851 to 5,005,536, forward strand). Ensembl gene ENSG00000176798.
Subcellular location: Cell membrane
Pathways (Reactome):
Sensory Perception: Expression and translocation of olfactory receptors; Olfactory Signaling Pathway
Gene Ontology:
Molecular function: olfactory receptor activity; G protein-coupled receptor activity; signaling receptor activity
Biological process: cellular response to lipid; detection of chemical stimulus involved in sensory perception of smell; G protein-coupled receptor signaling pathway; system process
Cellular component: plasma membrane; membrane
Genetic constraint (gnomAD): Loss-of-function variants: 2 observed, 2.82 expected, observed/expected ratio (o/e) 0.71, 90% interval 0.28 to 1.77. That is too few expected variants to judge how well the gene tolerates losing a copy. Missense variants: 378 observed, 401.68 expected, observed/expected ratio (o/e) 0.94, 90% interval 0.86 to 1.02. Synonymous variants: 156 observed, 152.91 expected, observed/expected ratio (o/e) 1.02, 90% interval 0.89 to 1.16.
Homologues: Orthologues: chimpanzee OR51L1 (99% identical), mouse Or51l1 (88% identical), rat Or51l1 (88% identical), dog OR51L1 (87% identical), rabbit OR51L1 (87% identical), pig OR51L1 (84% identical), tropical clawed frog or51ao1 (49% identical). Paralogues in human: OR51G2 (58% identical), OR51G1 (54% identical), OR51A7 (54% identical), OR51F2 (54% identical), OR51A4 (53% identical), OR51A2 (52% identical), OR51I2 (52% identical), OR51V1 (52% identical), OR51Q1 (51% identical), OR51B5 (50% identical), OR51C1 (49% identical), OR51I1 (49% identical), and 39 more.